ERG (ETS transcription factor ERG)
Diseases named in the same sentence as ERG in open-access papers (continued):
Sharing a sentence is not in itself a finding about the gene and the disease.
metastatic disease (25 papers, 1994 to 2026). "Restoration of miR-30b expression by src tyrosine kinase (Src) inhibitors was able to prolong survival and reduce metastatic disease of VCaP-derived xenograft mice by negatively regulating TMPRSS2:ERG and downregulating EMT-associated as well as ERG target genes." (PMID 25250334, 2014). "Future clinical studies of such anti-ERG drugs can be modelled based on previous clinical trials for anti-metastatic drugs to target patients with metastatic disease of low burden." (PMID 28465491, 2017). "For rearrangements of TMPRSS2 and/or ERG, previous findings showed ERG rearrangements in 30–50% of localized prostate cancers and 40–50% of metastatic diseases." (PMID 24098661, 2013). "In metastatic disease the prevalence of TMPRSS2:ERG gene fusions was found to be similar to that observed in organ-confined prostate cancer." (PMID 20598135, 2010). "We have analysed tumour-derived material from 30 ET patients with well-documented clinical course (18 with localised and 12 with metastatic disease at diagnosis) for the presence of EWS/FLI-1 or EWS/ERG RNA." (PMID 7524604, 1994). "This association holds up when comparing benign and tumor cells, as well as comparing within primary or metastatic tumor cohorts, and remains significant when cases are stratified by molecular alterations associated with FASN expression, such as ERG gene fusions." (PMID 38112617, 2024). "Our preclinical data suggest that SPOP inhibition may be effective in clinical settings where ERG is robustly expressed (e.g., neo-adjuvant setting or early metastatic disease)." (PMID 33531470, 2021). "While the TMPRSS2:ERG fusion gene is an early event of prostate tumorigenesis and associated with progression from HGPIN to adenocarcinoma, the role of this genetic alteration in more advanced and metastatic disease has also been recently investigated." (PMID 33634124, 2021). "The prevalence of anti-ERG AAbs represents a potentially important biomarker that can not only be used to stratify CaP patients but also predict the potential for biochemical recurrence or metastatic disease." (PMID 28191285, 2016). "Immunohistochemical staining yielded positive results for ERG, CD31, CD34 and CD117, and echocardiography identified a large tricuspid valve mass, suggesting metastatic disease." (PMID 40900681, 2025). "Therapeutic interventions in gene fusions targeting ERG and other ETS family members are an important opportunity to derive novel inhibitors that could substitute the current chemotherapies to treat resistant and metastatic disease." (PMID 31850193, 2019).
prostate (23 papers, 2011 to 2025). "Taken together, these results place EGFR as a mediator of ETV1 oncogenic activity both in early and advanced prostate carcinogenesis, while ERG overexpression seems to indirectly repress EGFR activation in early PCa carcinogenesis." (PMID 40808640, 2025). "While ERG overexpression has long been recognized as a pro-oncogenic factor in PCa23,24,27, transgenic expression of ERG alone is insufficient to induce prostate tumorigenesis in mice at age up to one year." (PMID 37537199, 2023). "In keeping with previous studies, our findings support the concept of ERG rearrangement being an early event in prostate carcinogenesis." (PMID 29088771, 2017). "A recent study has shown that ERG is a repressor of NKX3.1 raising the possibility of a feed-forward circuit in prostate tumorigenesis." (PMID 24418414, 2014). "In prostatic SCC, it has been found that ERG rearrangements in nearly half of SCC of the prostate is a similar rate of the same rearrangements in prostatic acinar carcinomas; and these rearrangements have not been detected in SCC of the urinary bladder or lung." (PMID 25042800, 2014). "We further show that overexpressed ERG and β-Catenin co-occupy sites in pyrimidine synthesis gene (PSG) loci and promote pyrimidine synthesis and prostate oncogenesis." (PMID 37537199, 2023). "In the specific case of TMPRSS2-ERG, the androgen sensitivity of the TMPRSS2 promoter is responsible for the steroid-dependent expression of oncogene ERG in prostate epithelium, a key event in prostate carcinogenesis." (PMID 27285981, 2016). "The genetic fusion between the erythroblast transformation-specific (ETS) transcriptional factor ETS-related gene (ERG) and the androgen-responsive promotor transmembrane protease, serine 2 (TMPRSS2) is suggested to be a major mechanism driving prostate carcinogenesis." (PMID 27276682, 2016). "The fusions that involve the ERG gene (such as the TMPRSS2:ERG fusion) and other members of the ETS transcription factor family have been extensively studied in PCa and proved to play an important role in prostate carcinogenesis." (PMID 26854164, 2015). "However, we also found that a mutant version of ERG that can activate, but cannot repress genes, can drive prostate tumorigenesis without activation of AKT, but this mutant ERG cannot promote luminal differentiation." (PMID 34314419, 2021).
prostatic intraepithelial neoplasia (22 papers, 2010 to 2025). "Recent studies suggest that prostatic intraepithelial neoplasia (PIN) can advance to invasive cancer when ERG activation coincides with loss of PTEN function." (PMID 40165885, 2025). "PCa individuals exhibiting ERG-positive high-grade prostatic intraepithelial neoplasia (HGPIN) are at a considerably elevated risk of developing PCa emphasising the clinical relevance of ERG as a potential biomarker for disease stratification and risk assessment." (PMID 40165885, 2025). "Consistently, transgenic overexpression of ERG in mouse prostate tissue accelerated the progression of high-grade prostatic intraepithelial neoplasia (HGPIN) to prostatic adenocarcinoma in a heterozygous Pten background." (PMID 40427154, 2025). "ERG overexpression is a driver event in the transition from prostatic intraepithelial neoplasia to carcinoma." (PMID 35203446, 2022). "Another study indicated that ERG gene alterations represent an initiating event that favors epithelial atypia and further progression to high-grade prostatic intraepithelial neoplasia and cancer." (PMID 26887047, 2016). "Importantly, the ectopic expression of a cocktail of factors including activated AKT (myristoylated AKT), ERG, and AR only in the basal epithelial cells resulted in prostatic intraepithelial neoplasia (PIN) and PCs in NSG mice." (PMID 30934773, 2019). "The results have not been always concordant: some studies suggest that ERG or ETV1 overexpression promotes pre-malignant in situ lesions (equivalent to prostatic intraepithelial neoplasia, PIN), whereas other studies suggest that this overexpression is not sufficient to cause the onset of cancer." (PMID 32791988, 2020). "In genetically modified mice, ERG or ETV1 overexpression leads to prostatic intraepithelial neoplasia (PIN) but not invasive cancer and crossbreeding with Pten-knockout mice results in PIN and micro-invasive cancer." (PMID 40427154, 2025).
breast carcinoma (20 papers, 2007 to 2024). "In luminal breast cancer, PIK3CB, ACVR18, HGF, and ERG were identified as the key genes with varying mutation frequencies between the luminal HER2-low and luminal HER2-0 subgroup." (PMID 39648226, 2024). "Under these conditions, we found that lower expression of ERG was significantly related to poor prognosis in melanoma (overall survival), breast cancer (disease-specific survival), and lung cancer (overall survival)." (PMID 30500808, 2018). "The analysis revealed differences in distant metastasis/recurrence time between the clusters, suggesting that the combined MRG and ERG gene set could distinguish the distant metastasis status of breast cancer patients." (PMID 38875364, 2024). "In ten patients with breast cancer tested by ERG FISH to evaluate ERG hybridization background in CTCs, numbers of ERG-rearranged CTCs were found to be below this threshold." (PMID 27391263, 2016). "The lncRNAs may act as competing endogenous RNAs (ceRNAs) and interfere in the binding of miR-190b to certain targets such as ERG, STK38L, and FNDC3A and thus contribute to breast cancer pathogenesis." (PMID 33976257, 2021). "Hybridization background of ERG probes was evaluated in a negative cohort of 10 breast cancer patients where the median value of ERG-rearranged cells was 0 cell/3ml blood (range 0-6/3ml)." (PMID 27391263, 2016). "For example, miR-196a has been studied for its oncogenic roles in glioblastoma, pancreatic adenocarcinoma, breast cancer, oesophageal adenocarcinoma, and colorectal cancer, and shown to target HOX family genes (HOXA7, HoxB7, HOXC8, HOXB8, HOXD8), ERG, HMGA2, ANXA1, S100A9, SPRR2C, KRTS." (PMID 24621885, 2014). "Thus, in ERG-positive high-grade tumors (Gleason greater than 4+3), expressing a high level of LINC02418, the MELK inhibitor OTS167 could be a promising therapeutic opportunity, because it is already utilized in clinical trials for the treatment of breast cancer and onco-hematological pathologies." (PMID 33672425, 2021).
sarcoma (18 papers, 2011 to 2025). A usually aggressive malignant neoplasm of the soft tissue or bone. "The vast majority of CIC–DUX4 sarcomas express ERG and FLI1, as frequently as in classic ES, representing an important diagnostic challenge in differential diagnosis." (PMID 32155762, 2020). "We found that PRMT1 and PRMT5 expression, along with MEP50 the obligate cofactor of PRMT5, are generally higher in multiple sarcoma types, including EWSR1::FLI1 and EWSR1::ERG fusion-positive ES tumours, than in breast and lung cancer." (PMID 40823091, 2025). "An initial panel of markers should be done to identify the lineage of tumor: carcinoma (cytokeratin AE1/3, OSCAR, CAM5.2), lymphoma (CD20, CD3), melanoma (S-100 protein, SOX10), and sarcoma (desmin, smooth muscle actin, MDM2, ERG)." (PMID 39634259, 2024). "A fusion protein involving the DNA-binding domain of a transcription factor, such as DDIT3 or ERG, and the LC domain of FUS can redirect RNA Pol II activity sufficient to drive Ewing and other sarcomas." (PMID 37690693, 2023). "Chi-squared analysis demonstrated a statistical difference between EWSR1-FLI1/ERG and EWSR1-NFATc2 positive sarcomas across all genes included in the dataset (p < 0.001)." (PMID 34021224, 2021). "The morphology was not typical for gastroblastoma and was negative for CD99, ERG, and WT1, which were against CIC/DUX sarcoma." (PMID 36928336, 2023).
lung carcinoma (17 papers, 2011 to 2025). "Our results indicated the regulation network of ERG in lung cancer." (PMID 38495494, 2024). "TGFBR2, FLI1, ERG and NTRK3 were shared DEmRNAs of hsa‐mir‐9‐1, hsa‐mir‐9‐2 and hsa‐mir‐9‐3, which suggested that mir‐9 might play a crucial role in LUAD by regulating these four lung cancer‐related genes." (PMID 30761256, 2019).
acute lymphoblastic leukemia (16 papers, 2012 to 2025). Leukemia with an acute onset, characterized by the presence of lymphoblasts in the bone marrow and the peripheral blood. "The aberrant expression of ERG is not limited to MM; it is also implicated in other hematologic malignancies, including acute lymphoblastic leukemia (ALL) and lymphoma." (PMID 40741330, 2025). "ERG is deleted in a subset of acute lymphoblastic leukemias, which may facilitate transformation, and is suggestive of a role for ERG in DS childhood leukemia." (PMID 22461792, 2012). "Haptad regulated stem cell enhancers enhanced ERG transcription and promoted AML and T-ALL (acute lymphoblastic leukemia)." (PMID 33842551, 2021). "Intragenic ERG deletions occur in 3–5% of B-cell precursor acute lymphoblastic leukemia, specifically in B-other subtype lacking the classifying genetic lesions." (PMID 27494621, 2016). "However, we did not confirm expression of the proteins in acute lymphoblastic leukemia cases with endogenous ERG deletion." (PMID 27494621, 2016). "A recently characterized high-risk subgroup in acute lymphoblastic leukemia (ALL) is defined by the IKZF1plus profile, which is marked by the co-occurrence of IKZF1 deletions alongside deletions in CDKN2A/B, PAX5, or the PAR1 region, in the absence of ERG gene alterations." (PMID 41228238, 2025). "Moreover, a RAG-dependent ERG deletion or alternative transcript, following DUX4-IGH rearrangement, has been shown to promote B-cell precursor acute lymphoblastic leukemia (ALL) with a favorable outcome." (PMID 37735473, 2023). "Additionally, we identified a single individual with B-cell precursor acute lymphoid leukemia with two intragenic deletions involving IKZF1 and PAX5, in the absence of an ERG deletion, suggestive of the IKZF1plus phenotype." (PMID 37686670, 2023).
melanoma (14 papers, 2011 to 2025). A malignant, usually aggressive tumor composed of atypical, neoplastic melanocytes. "More investigation on EndMT in tumour microenvironment revealed the role of two transcription factors in EndMT in melanoma, ERG, and FLI1." (PMID 36077754, 2022). "In contrast, within tumors formed after subcutaneous injection of B16F10 melanoma cells, some ECs showed reduced expression of ERG and FLI1." (PMID 30500808, 2018). "Melanoma tumours also display reduced expression of ERG and FLI1 in tumour endothelial cells." (PMID 36077754, 2022). "Moreover, lower expression of ERG in melanoma samples has been related to poor prognosis and overall survival." (PMID 36077754, 2022). "In particular, ELK3, ETS1, ETV1, ETV4, ETV5, and SPI1 were significantly upregulated in melanoma, whereas EHF, ELF3, ELF5, ERG, ETS2, ETV7, and SPDEF were significantly downregulated in the tumor." (PMID 33424867, 2020). "The case presented in this paper is only the second reported melanoma with angiosarcomatoid dedifferentiation highlighted by immunohistochemical expression of ERG and CD31, while lacking expression of MelanA and PRAME." (PMID 39001214, 2024). "For example, ERG, ETV1, and ETV4 can be upregulated in prostrate cancers, and ETV1 is upregulated in post gastrointestinal stromal tumors and in more than 40% of melanomas." (PMID 26683696, 2015). "Next, we investigated whether ERG is involved in pathological angiogenesis, using the B16F0 melanoma tumor model, which depends on angiogenesis for growth." (PMID 25584796, 2015).
osteosarcoma (11 papers, 2017 to 2023). A usually aggressive malignant bone-forming mesenchymal neoplasm, predominantly affecting adolescents and young adults. "BMSC-derived exosomes, which express the lncRNA PVT1 in abundance, promoted osteosarcoma growth and metastasis by regulating the miR-183-5p/ERG axis." (PMID 37377390, 2023). "In a previous study, exosomes secreted by bone marrow mesenchymal stem cells (BMSCs) transfer lncPVT1 into osteosarcoma cells; the upregulation of lncPVT1 can promote ERG expression by inhibiting ERG ubiquitination and sponging miR-183-5p." (PMID 35965522, 2022). "The ubiquitination assay was also performed in PVT1-interfering osteosarcoma cells after being co-cultured with BMSC-EXO, and the result demonstrated that PVT1 in exosomes inhibited ubiquitination of ERG protein in osteosarcoma cells." (PMID 31699956, 2019). "Meanwhile, the co-transfection of si-PVT1 and miR-183-5p inhibitor restored the ERG protein expression which was reduced by interfering PVT1 in three osteosarcoma cell lines." (PMID 31699956, 2019). "The co-culturing of BMSC-EXO and ERG-interfering MNNG/HOS cells (MNNG/HOSsi-ERG) reduced the malignancy of osteosarcoma cells, while the co-culturing of BMSC-EXO and Ets-1-interfering MNNG/HOS cells (MNNG/HOSsi-Ets-1) did not negate such response." (PMID 31699956, 2019). "Taken together, these data indicated that PVT1 in BMSC-EXO promotes osteosarcoma growth and metastasis via increasing ERG." (PMID 31699956, 2019). "We then overexpressed PVT1 in three osteosarcoma cell lines, and immunoblotted Ub-ERG using ubiquitination assay." (PMID 31699956, 2019). "In summary, our findings indicated that BMSC-derived exosomes encapsulate PVTl and transport it into osteosarcoma cells, and the transported PVT1 promotes tumor growth and metastasis by inhibiting ubiquitination and promoting expression of ERG in osteosarcoma cells." (PMID 31699956, 2019). "The direct binding between PVT1 and the oncogenic protein ERG was confirmed using RNA immunoprecipitation and RNA pull-down assays, and the transported PVT1 promotes osteosarcoma cell proliferation and migration via inhibiting degradation and ubiquitination of ERG." (PMID 31699956, 2019). "However, whether ERG affects the progression of osteosarcoma through other mechanisms still needs more investigations." (PMID 31699956, 2019). "In addition, our findings indicated that PVT1 in BMSC-derived exosomes promotes osteosarcoma cell proliferation and migration via increasing ERG, an oncogenic protein in osteosarcoma, suggesting interfering PVT1 in exosomes as a therapeutic target of osteosarcoma." (PMID 31699956, 2019). "We confirmed these findings using another ERG-positive cancer cell line, the MG63 osteosarcoma cell line." (PMID 32581342, 2020). "Meanwhile, the BMSC-derived exosomes promote osteosarcoma growth and metastasis via PVT1/ERG pathway." (PMID 31699956, 2019). "As Ets-1 is a well-defined pro-metastatic factor in osteosarcoma, we supposed that the pro-metastatic effect of PVT1 in BMSC-EXO was exerted via specifically raising ERG expression." (PMID 31699956, 2019). "Given that the PVT1 in BMSC-EXO increased ERG protein expression via inhibiting ubiquitination and sponging miR-183-5p, we investigated the mechanism of PVT1 on osteosarcoma cell proliferation and migration." (PMID 31699956, 2019). "On one hand, PVT1 can combine with miR-183 to promote ERG expression, on the other hand, PVT1 can directly combine with ERG to inhibit its ubiquitination degradation, and finally enhance the growth and metastasis of osteosarcoma." (PMID 36309693, 2022).
vascular tumors (11 papers, 2014 to 2025). "For instance, one recent study demonstrated strong endothelial immunoreactivity for ERG in both benign and malignant vascular tumors, as well as other vascular lesions, including arteriovenous malformations (AVMs) and papillary endothelial hyperplasia." (PMID 25881913, 2015). "Evidence has also demonstrated the presence of ERG overexpression within various non-vascular neoplasms, including prostate carcinoma, Ewing’s sarcoma, and acute myeloid leukemia." (PMID 25881913, 2015). "Despite these limitations, ERG remains a highly specific marker for vascular neoplasms in general." (PMID 40666093, 2025). "The immunophenotype in all cases was consistent with the known character of this vascular tumour, displaying positivity for the typical endothelial cell markers CD31, CD34 and ERG." (PMID 37686662, 2023). "In our case, immunoreactivity for GATA3, estrogen, and progesterone receptors confirmed the breast tissue origin, while negative PAX8 and ERG stains ruled out Müllerian origin and vascular neoplasms, respectively." (PMID 41393763, 2025). "However, ERG expression is not exclusive to AS as nuclear ERG staining has been observed in various benign or malignant vascular tumors, including hemangioma, lymphangiomas, epithelioid hemangioendotheliomas, and Kaposi sarcoma." (PMID 40666093, 2025). "Furthermore, we considered the possibility of a cutaneous malignant vascular neoplasm, but again the vascular markers including ERG, CD31, and CD34, were all negative." (PMID 35639915, 2022). "ERG and FLI1 are relatively sensitive and specific markers of vascular tumors, regardless of the type and level of malignancy 9,10." (PMID 39845895, 2024).